IL10 (interleukin 10)
Diseases named in the same sentence as IL10 in open-access papers (continued):
Sharing a sentence is not in itself a finding about the gene and the disease.
tumor (continued). "Using bioinformatics analysis and clinical specimens, we found that peritumoral macrophages expressed higher anti-inflammatory factor IL-10 and lower pro-inflammatory factor IFN-g/TNFa than macrophages in tumor tissues, and were associated with local invasion, tumor recurrence, and metastasis." (PMID 40756343, 2025). "Previous studies have reported that tumor-associated macrophages (TAMs) primarily secrete anti-inflammatory cytokines such as ARG-1, IL-10, and TGF-β to generate an anti-inflammatory response, participate in tumor angiogenesis and extracellular matrix remodeling." (PMID 40463876, 2025). "Notably, our combination therapy effectively counteracts the immunosuppressive TME by reducing M-MDSC and Treg infiltration, which are known to promote tumor progression through secreting inhibitory cytokines (IL-6, IL-10, and TGF-β)." (PMID 40625660, 2025). "When stimulated with tumor antigens, a notable increase in IL-10 secretion was observed." (PMID 41019059, 2025). "Moreover, Tgfb and Il10 expression in the peritumoral area was statistically significantly higher in comparison with the tumor tissue." (PMID 39063041, 2024). "Thus, patients with higher tumor burden despite therapy had the lowest IL-10 production already at baseline." (PMID 38473247, 2024). "M2-type macrophages then secrete epidermal growth factor receptor (EGFR), transforming growth factor-β (TGF-β), vascular endothelial growth factor (VEGF), platelet-derived growth factor (PDGF), IL-10, IL-6 and arginase-1, promoting tumor angiogenesis and tumor progression." (PMID 38792234, 2024). "IL-10 may either support or inhibit tumor development, depending on factors such as the type of cancer, the stage of disease, and the local tumor microenvironment." (PMID 39132165, 2024). "Increased HIF-2α levels are associated with diminished numbers of tumor-infiltrating CD8+ lymphocytes and promote stem cell factor (SCF) production, which in turn increases IL-10 and TGF-β secretion that ultimately contributes to an immunosuppressive tumor environment." (PMID 38339352, 2024). "Moreover, the exist of tumor, increased level of IL-6, IL-10, and decreased lymphocyte subset counts correlated to a poor outcome." (PMID 38173531, 2024). "Finally, patients with tumor, or high IL-6 or high IL-10 expression and lower CD8+ or lower NK levels exhibited a significantly shorter survival time." (PMID 38173531, 2024). "The anti-inflammatory properties foster the pro-tumor image of IL-10." (PMID 39204319, 2024). "Importantly, qRT-PCR and immunofluorescence analyses also revealed that double treatment, with both a-Egfl6 and a-PD-L1, reduced tumor expression levels of both IL-10 and Cxcl2." (PMID 39312740, 2024). "Once Tregs reach the tumor, differentiation/polarization and activation is induced by a variety of tumor- and immune-derived factors, including TGFβ, IL-10, PGE2/COX2, IL-35, adenosine, IL-6/STAT3, and even has_circ_0069313, a tumor-derived circular RNA that helps Tregs maintain FoxP3 levels." (PMID 38254801, 2024). "Here, we found that MEIS2 can regulate the expression level of IL10 to affect the infiltration of myeloid cells, which may be helpful to understand why IL10 facilitates the formation of immunosuppressive niche in tumor." (PMID 38711262, 2024). "Similarly, Smad4 deletion in S100A4+ cells down-regulated the expression of M1-like factors such as iNOS and IL-12 and up-regulated the expression of M2-related genes such as Arg1 and IL-10 in CRC tumor tissues." (PMID 39664586, 2024). "Likewise, tumor-targeted oncolytic vaccinia virus (VV) with deleted thymidine kinase armed with murine IL-10 (VVLΔTK-IL-10) was developed." (PMID 39337402, 2024). "In addition, the accumulation of other immunosuppressive factors in tumor tissue, such as IL-1 and IL-10, can also weaken the effects of anti-tumor immunotherapy." (PMID 38534538, 2024).
tumor (continued). "IL-10, secreted by both HRS cells and tumor-associated macrophages (TAMs), suppresses Th1-mediated immunity and cytotoxic T cell activation, while TGF-β inhibits T cell proliferation and promotes fibrosis, which is a hallmark of the nodular sclerosis subtype of cHL." (PMID 39682256, 2024). "Additionally, pancreatic cancers secrete high levels of immunosuppressive cytokines such as TGF-β and IL-10, creating a tumor microenvironment that hinders effective T-cell response." (PMID 39539544, 2024). "In contrast to classically activated Mφs that stimulate phagocytosis, inflammation, and host immunity, a prominent population of tumor Mφs undergo alternative, M2-like polarization to express anti-inflammatory molecules, such as IL-10, TGF-β, and arginase 1 to induce tumor immunosuppression." (PMID 38416830, 2024). "This correlates with the immunosuppressive activity induced by M2 macrophages in advanced stages of the neoplastic process and immunomodulation exerted by tumor cells and tumor-associated stromal cells through cytokines as TGF-β and IL-10 as well as surface receptors like PD-L119,41,44." (PMID 38956203, 2024). "By reducing IL10RB levels, physical activity may limit IL-10-driven immunosuppressive signaling, thereby shifting the tumor microenvironment towards a state more conducive to effective anti-tumor immunity." (PMID 39769247, 2024). "A high expression level of IL-10 in the tumor microenvironment might be involved in the progression of HCC." (PMID 38693593, 2024). "In addition, targeting the complement C3aR/C5aR/IL-10 pathway has been suggested in conjunction with other therapeutic modalities because it enhances the anti-tumor efficacy of T cells." (PMID 38918278, 2024). "In CRC, IL-10 primarily affects tumor development by regulating immune and inflammatory responses." (PMID 38562480, 2024). "However, recent research has revealed that IL-10 possesses both pro- and anti-tumor properties, increasing interest in its potential for cytokine-based cancer immunotherapies." (PMID 39411143, 2024). "There have also been developed cell-free tumour vaccines containing α-fetoprotein-enriched DC-derived exosomes, which stimulate immune cells to produce IFN-γ and IL-2 and reduce the expression of TGFβ and IL-10 at the site of the tumour, thus, inducing antigen-specific response to cancer cells." (PMID 38200509, 2024). "For example, increased expression of immune suppressive cytokines, such as transforming growth factor β (TGF-β), vascular endothelial growth factor (VEGF) and interleukin 10 (IL10) may inhibit anti-tumour immune response." (PMID 39001359, 2024). "IL‐10 is capable of restraining the growth of tumours by suppressing Th17 T cells and macrophages." (PMID 38647237, 2024). "IL-10 also supports immune tolerance within the tumor, thereby aiding its growth and spread." (PMID 39207449, 2024). "Immunosuppressive mechanisms of PDAC cells include editing the immune system to become unrecognisable leading to tumour escape, activation, and release of immunosuppressive molecules such as IL-10 and TGFβ which inhibit immune response and promote tumour growth and metastasis." (PMID 38973003, 2024). "TAMs, induced by tumor activated HIF1α, could secrete IL-23, thereby promoting the proliferation of Tregs and the expression of IL-10 and TGF-β." (PMID 38957393, 2024). "The tumor suppressor role of MEIS2 is partially mediated by downregulation of IL10." (PMID 38711262, 2024). "Tregs exert immune suppression on anti-tumor responses by competing with effector T cells for costimulatory molecules on antigen-presenting cells and by secreting immunosuppressive molecules such as IL-10 and adenosine." (PMID 39346737, 2024). "Tregs could secrete inhibitory cytokines, such as interleukin-10 and transforming growth factor-β, attenuate the activity of nature killer (NK) cells and cytotoxic T cells and dampen the body’s anti-tumor immune surveillance." (PMID 39093404, 2024).
tumor (continued). "The main role of IL-10 at the onset of tumor formation may be to stimulate NK cells and CTL-mediated killing of tumor cells." (PMID 38349555, 2024). "Furthermore, overexpression of let-7d in RCC cells was found to inhibit intertumoral M2 TAM polarization and consequent tumor angiogenesis by targeting IL-10 and IL-13." (PMID 39169402, 2024). "Interestingly, when TAMs are polarized to be M2-like by IL-10, autocrine secretion of IL-10 increases, facilitating tumor growth, invasion and metastasis." (PMID 39525623, 2024). "Collectively, it is quite clear that the circRNAs that inhibit IL-10 production from tumour cells act as tumour suppressors, while those that increase the production of IL-10 from tumour cells promote oncogenesis, cell survival, drug resistance and mediate immunosuppression." (PMID 38186186, 2024). "On the other hand, CD206-expressing monocytic cells are classically associated with an anti-inflammatory phenotype, as described for in vitro differentiated regulatory macrophages or infiltrating CD14+ CD206+ tumor monocytes, which specifically express Arginase-1, IL-10, and TGFβ." (PMID 39845960, 2024). "The infiltration and polarization of macrophages within tumors, along with the levels of IL-10 and IL-12 in the tumor supernatant, collectively indicated a shift from M2 to M1 polarization of tumor-associated macrophages upon treatment with PTX/ICG-NVs@Au@CAT under laser irradiation." (PMID 38544975, 2024). "These novel findings suggest that IL-10 in the BM drives generation of immature regenerative cells with diverse lineage potential but tumor-residing progenitors have advanced maturity acquired either at an extramedullar site or in response to tumor-specific cues." (PMID 38640116, 2024). "TAMs are characterized by an M2 phenotype, promoting tumor growth, angiogenesis, and metastasis and suppressing antitumor immune responses through the secretion of anti-inflammatory cytokines and growth factors such as IL-10 and TGF-β." (PMID 39766138, 2024). "Immune suppressive cells within the TME, such as regulatory T cells (Tregs), MDSCs, and tumor-associated macrophages (TAMs), secrete immunosuppressive molecules like transforming growth factor-beta (TGF-β), interleukin-10 (IL-10), and programmed cell death ligand 1 (PD-L1)." (PMID 38886844, 2024). "Tumor-infiltrated Tregs with higher expression of CCR8 produced more IL10 molecules in vitro." (PMID 38169378, 2024). "Moreover, IL-10 suppression enhanced both anti-tumor activity and responses to checkpoint blockade in CLL." (PMID 39281678, 2024). "Other studies have reported models focusing on one or on parallel pathways of inhibitory factors induced by Treg, TGF-β and/or IL-10 that promote tumor growth and reduce the cytotoxicity of effector cells (i.e., CD8+ cells and others such as DC, CD4+ helper T cells, and IL-2)." (PMID 39598584, 2024). "Similarly, analysis of macrophages in the tumor microenvironment shows that M2-type macrophages promote tumor growth and suppress immune responses by secreting molecules like IL-10 and upregulating PD-L1, aiding tumor cells in evading immune surveillance." (PMID 39539544, 2024). "Other myokines like IL-6 and IL-15 contribute to tumor suppression by hindering adipogenesis, while IL-6, IL-10, and IL-8 can bolster immune cell activity, enhancing their numbers and cytotoxic capabilities, thereby fostering a “hot” immune microenvironment conducive to fighting cancer." (PMID 39346906, 2024). "In cases of U-CLL, where IL-10 production is reduced, a higher tumor load might compensate for this decrease, contributing to the clinical immunosuppression observed in both CLL subsets." (PMID 38339076, 2024). "This relationship underscores the potential of IL-10 to enhance tumor-specific immune surveillance while also controlling pathogenic inflammation, which could contribute to its emerging role as a key player in cancer pathology." (PMID 38672104, 2024).
tumor (continued). "In addition to increasing Tregs and promoting IL-10 production in the tumor microenvironment, tumors utilize inhibitory immune signaling pathways through direct cell-to-cell interactions." (PMID 38594256, 2024). "That may be the result of multiple origin of TGF-β and VEGFA, but IL-10 is mainly produced by tumor infiltrated T cells." (PMID 38554155, 2024). "Furthermore, they drive the recruitment of IL10+ regulatory T cells (Tregs), promoting a highly suppressive tumor microenvironment." (PMID 39456552, 2024). "Immunosuppressive IL-10 produced by TAMs could enhance tumor cell survival, proliferation, and metastasis by the inhibition of NK and cytotoxic T cells (CTL) cells." (PMID 38997411, 2024). "This suggests that the role of IL-10 in the Aurora-A knockdown CT26-derived tumor model is subtle." (PMID 38291041, 2024). "Additionally, CM treatment boosted moMDSCs production of IL-6, IL-10, and PGE2, soluble mediators associated with tumor-promoting inflammation." (PMID 38343540, 2024). "Studies have also shown that FOXP3-positive regulatory T cells in the tumor microenvironment secrete immunosuppressive cytokines such as IL-10 and TGF-β, inhibiting cytotoxic T cells and enabling tumor cells to evade immune surveillance in various cancer types." (PMID 40741180, 2024). "Compared to TNF-α, IL-10 and IL-17 play a more direct role in the mechanism of tumor immune escape." (PMID 38734702, 2024). "However, IL-10 released by macrophages or other immunosuppressive cells, as well as tumor-derived factors like Vascular endothelial growth factor, can inhibit the maturation of conventional dendritic cells and directly inhibit their production of IL-128." (PMID 38755255, 2024). "M1 macrophages predominantly secrete interleukin-12 (IL-12) and exhibit anti-tumor properties, while M2 macrophages primarily produce interleukin-10 (IL-10) and promote desmoplasia, immunosuppression and, in turn, cancer progression through the activation of the PI3Kγ pathway." (PMID 39199647, 2024). "BMSCs recruited to the tumor microenvironment differentiate into tumor-associated fibroblasts (TAF), which release IL-6, IL-10, C-C chemokine ligand 5 (CCL5), and extracellular matrix remodeling enzymes in the tumor microenvironment to affect tumor cell survival and angiogenesis." (PMID 38770000, 2024). "In addition, tumor suppressor cells in the area around the tumor (such as TAMs and Tregs) control the immune response and help the tumor grow and spread by releasing immunosuppressive substances such as IL-10 and TGF-β." (PMID 39194667, 2024). "MDSCs can polarize macrophages toward the M2 phenotype, which promotes tumor progression, secrete IL-10 and TGF-β, induce the proliferation of Treg cells, and indirectly inhibit CD4+ Th1 and CD8+ T cell activity through the inhibition of DCs, exerting immunosuppressive functions." (PMID 38404689, 2024). "Cytokines such as transforming growth factor β and IL-10 could also be added to this system to further model the inhibitory tumor microenvironment, providing a useful and flexible platform for screening immunotherapeutics." (PMID 39657666, 2024). "TAM and tumor stromal cells have been suggested to release IL-10 and TGF-β." (PMID 38384472, 2024). "However, CXCL13 can induce B cells to produce the immunosuppressive cytokine IL‐10 in tumor tissues." (PMID 39344390, 2024). "Therefore, varied secretion of two cytokines (IL-10 and IL-12p35) from their usual levels, from mouse BMDCs, were considered as functional readouts to understand the influences of tumor as well as of NLGP on these cells." (PMID 38649988, 2024). "IL-10 is an anti-inflammatory cytokine known to modulate immune responses and maintain immune homeostasis, while IL-17 is involved in promoting pro-inflammatory responses, contributing to tumor development." (PMID 39456637, 2024).
tumor (continued). "Subsequently, to test whether YTHDF1 regulated the immunosuppressive tumor microenvironment, the immunosuppressive cytokines (IL-10, TGF-β) and immune effector cytokines (IFN-γ, IL-2) were tested." (PMID 39557826, 2024). "In addition, tumor cells can produce cytokines including IL-10, allowing tumor cells to escape the clearance of CTL.." (PMID 39290709, 2024). "TDSFs, such as the vascular endothelial growth factor (VEGF), tumor necrosis factor alpha (TNF-α), transforming growth factor-β (TGF-β), and interleukins (ILs), such as IL-6 and IL-10, can derive from tumor cells, which are themselves induced by the local inflammatory microenvironment." (PMID 38391950, 2024). "Interestingly, STING ablation enhanced CD8+ T-lymphocyte infiltration, increased anti-tumour activity, reduced myeloid-derived suppressor cell infiltration, and decreased IL-10 production." (PMID 39403376, 2024). "Notably, in vitro, xenograft model indicated that CAFs can facilitate tumor progression through the IL-10/JAK1/STAT3 signaling pathway." (PMID 39511039, 2024). "Furthermore, CSF-1R inhibition in CAFs led to a reduction in IL-10 production and an increase in IL-12 production in macrophages and enhanced the cytotoxicity of macrophages against tumor cells, indicating a shift towards an anti-tumor M1-like phenotype." (PMID 39457693, 2024). "This process happens due to overstimulation, chronic tumor antigenic exposure, hypoxia, presence of regulatory T cells (Tregs) or myeloid-derived suppressor cells (MDSCs), and immunosuppressive cytokines [interleukin-10 (IL-10) and transforming growth factor-β (TGF-β)]." (PMID 39072334, 2024). "In addition, tumor-derived exosomal miR-6794-5p promoted M2 polarization and the secretion of IL-10 by macrophages by activating the JAK1/STAT3 pathway, ultimately promoting tumor malignancy." (PMID 38521953, 2024). "The hypoxia of tumor microenvironment suppresses metabolic activity and viability of DCs, or tumor cells reduce the immune activity of dendritic cells directly by secreting interleukin-6 (IL-6), interleukin-10 (IL-10), and transforming growth factor-β (TGF-β)." (PMID 38231384, 2024). "It was observed that the increased tumor development in IL-10−/− mice resulted from multiple intertwined mechanisms: increased immunosuppression, enhanced inflammation, and possible reduced effector T cell function and tumor trafficking in tumor-bearing hosts." (PMID 38473247, 2024). "Conversely, blockade of interleukin-10 signaling preferentially enhanced the capacity of CD8+ T cells to secrete Interferon gamma when being cocultured with CBM588-primed lamina propria mononuclear cells of tumor-bearing mice." (PMID 38385162, 2024). "IL-10 is secreted both by tumor and immune infiltrates, including lymphocytes and macrophages." (PMID 39057050, 2024). "Genetic depletion of either Nrp2a or Nrp2b in macrophages in vitro inhibited phagocytosis/endosomal processing of apoptotic tumor cells, increased tumor cell migration in response to culture with Nrp2aKO/Nrp2bKO macrophage supernatants, and decreased IL-10 production in response to LPS." (PMID 38592275, 2024). "However, IL-12 production can be suppressed by IL-10 secreted by macrophages, tumor cells, and other immunosuppressive cells, as well as by tumor-derived factors, such as vascular endothelial growth factor (VEGF), that decrease cDC1 maturation." (PMID 38400148, 2024). "With the increased CD4+ Tregs and effector CD4+ T cells in FLC tumor, we hypothesized that IL-10 blockade could work in FLC in conjunction with blockade of PD-1 to reactive effector CD8+ and CD4+ T cells." (PMID 38429349, 2024). "M1 macrophages, which express high levels of pro‐inflammatory cytokines and MHCII are referred to as anti‐tumor, whereas M2 macrophages, which express high levels of immunosuppressive factors such as IL‐10 and transforming growth factor (TGF)‐β are referred to as pro‐tumorigenic." (PMID 38426622, 2024).